SNORD115-36 (small nucleolar RNA, C/D box 115-36)
Synonyms: HBII-52-36
Gene: Small nucleolar RNA gene on chromosome 15 (25,236,085 to 25,236,166, forward strand). Ensembl gene ENSG00000202499.
Gene Ontology:
Biological process: RNA processing
Cellular component: nucleolus
Homologues: Orthologues: macaque SNORD115 (100% identical). Paralogues in human: SNORD115-11 (100% identical), SNORD115-29 (100% identical), SNORD115-43 (100% identical), SNORD115-12 (99% identical), SNORD115-16 (99% identical), SNORD115-22 (99% identical), SNORD115-26 (99% identical), SNORD115-39 (99% identical), SNORD115-44 (99% identical), SNORD115-6 (99% identical), SNORD115-9 (99% identical), SNORD115-10 (98% identical), and 37 more.